IRF5 (interferon regulatory factor 5)
Diseases named in the same sentence as IRF5 in open-access papers (continued):
Sharing a sentence is not in itself a finding about the gene and the disease.
infection (68 papers, 2009 to 2025). The state of being infected such as from the introduction of a foreign agent such as serum, vaccine, antigenic substance or organism. "We observed significantly higher frequencies of cells co-expressing PD-1 and TIM-3 in IRF-5-deficient p14 cells over the entire course of infection, compared with the control group." (PMID 40494997, 2025). "Nevertheless, a skewed IRF-4/RF-5 balance cannot entirely explain the severe defects we observed in IRF-5-deficient CD8 T cells during the chronic phase of infection." (PMID 40494997, 2025). "Mice lacking Irf5 had a significant reduction in the number of neutrophils accumulating at the site of infection, and acute lung injury was markedly reduced in Irf5-deficient mice." (PMID 30515152, 2018). "Results showed that after infection with S. japonicum, there was more IRF5 in the nuclei of SR-A-deficient macrophages than WT cells." (PMID 28695899, 2017). "As expected, IRF-5-deficient mice had a lower expression of IL-6 during the first week of infection." (PMID 26046638, 2015). "In contrast, TNF mRNA levels were higher in Cre- mice compared to IRF-5 deficient mice during the first 2 weeks of infection." (PMID 26046638, 2015). "Conversely, IRF5 deficiency severely impaired the infiltration of inflammatory cells in the liver already at earlier stages of infection." (PMID 21811511, 2012). "Taken together, these results suggest that IRF-5 deficiency in p14 cells results in Irf5−/− p14 cells undergoing similar clonal expansion than WT p14 cells but then failing to survive during the chronic phase of infection." (PMID 40494997, 2025). "Hence, we decided to validate these findings in vivo and analyze the proportion of adoptively transferred IRF-5-sufficient and -deficient p14 cells that were in the G0, G1, and S-G2-M phase at d4, 8, 30, and 60 after infection with LCMV Cl13." (PMID 40494997, 2025). "Following infection, comparable viral loads were detected in WT and Irf5‐deficient mice." (PMID 33423291, 2021). "Although inflammation per se is restrained by standard-of-care drugs such as glucocorticosteroids and immunosuppressants, drug discontinuation, infection, or other environmental factors may trigger the amplification of such an IRF5-dependent vicious cycle, causing an SLE flare." (PMID 34282144, 2021). "While females adoptively transferred with Irf5−/− p14 cells survived infection to similar rate than those that received WT p14 cells, only 20% of male mice adoptively transferred with Irf5−/− p14 survived LCMV Cl13 infection at d15 p.i.." (PMID 40494997, 2025). "In HIV-1 (WT)–infected, GFP+ THP-1/PMA macrophages, we observed a marked increase in nuclear IRF5 staining that was blocked upon pretreatment with EFV or upon infection with HIV-1/M10 mutant virus." (PMID 40493408, 2025). "IRF5 function is cell-type specific and limited primarily to induce proinflammatory cytokines in response to infection." (PMID 40493408, 2025). "Other pro-inflammatory factors like IRF5, IL-12B, IL-1RN, IL-22, IL-8, and IL-33 significantly increased at 48 hpi in weaned piglets compared to newborn piglets after infection." (PMID 40589734, 2025). "IRF-5 expression was found to colocalize with the nucleus in CD8 T cells during the whole course of infection, with 50–70% of the cells expressing IRF-5 in the nucleus between d8 and 60 p.i.." (PMID 40494997, 2025). "In contrast, IRF-5 transcripts were detected in LmCen−/− infection on days 2 and 7, and in LmWT infection on days 7 only." (PMID 39702382, 2024). "In the present study, we observed that after 24 h of infection with rotavirus in HT-29 cells, the relative expression of IRF-5 and IFN-β was significantly (p < 0.05) increased, as compared with non-infected cells." (PMID 37317211, 2023). "In contrast, the expression of IRF5 mRNA was significantly repressed after miR-144/451 lentiviruses infection." (PMID 35967345, 2022).
infection (continued). "Some interferon regulatory factors (irf1, irf3, irf4b, irf5, irf6, irf8) continued to show upregulation during the later stages of infection (day 6 to day 10) in virus-infected fish spleens." (PMID 36016951, 2022). "Intranasal infection with IAV resulted in significantly increased Irf5 expression in whole lung homogenates of WT mice 3 and 7 days post‐infection (p.i.)." (PMID 33423291, 2021). "When we looked at different IRFs, we found that Irf7, Irf8, Irf5, and Irf4 were significantly upregulated in WT mouse brains upon infection with JEV." (PMID 34379515, 2021). "Our work suggests that an IRF5-dependent pathway acts locally in draining lymphoid tissue following infection with CHIKV, whereas IRF3/7-dependent pathways are activated at the site of inoculation." (PMID 31999809, 2020). "and monocytes, macrophages and DCs at d21 and 28), and CD11chiMHCIIhi (DCs at d0 and 14p.i and DC and inflammatory monocytes at d21 and 28p.i) dramatically increased during chronic stages of infection in IRF-5-sufficient control mice." (PMID 32038622, 2019). "During infection, transcription factor interferon regulatory factor 5 (IRF5) is essential for the control of host defense." (PMID 30902986, 2019). "In another study, expression of IRF5 was downregulated after 3 weeks of infection with MAP in the spleen of mice." (PMID 29698503, 2018). "In this study, we for the first time report a SR-A interacts with IRF5 to inhibit its nuclear translocation, resulting in an M2 polarization of macrophages and subsequently favouring adaptive Th2 responses on pathogen infection/stimulation." (PMID 28695899, 2017). "Infection of IRF5−/− human iPSdMs with C. trachomatis led to a 45.4±11.1% increase in bacterial load as compared to the parental KOLF2 iPSdMs." (PMID 28440293, 2017). "Our data suggest that IRF-5-mediate inflammation induced by Leishmania at early stages of infection plays a detrimental role in the development of protective CD8+ T cell responses." (PMID 26046638, 2015). "Our data shows that IRF-5 participates in limiting antigen-specific CD8+ T cell expansion at the very early stages of infection by indirectly inducing HIF-1α expression in DCs." (PMID 26046638, 2015). "In conclusion, we demonstrate that IRF-5-mediated inflammation induced by L. donovani at the onset of the infection participates in limiting CD8+ T cell expansion by upregulating HIF-1α in DCs and subsequently impairing DC functions." (PMID 26046638, 2015). "In the present study we have demonstrated that the TLR7-mediated activation of IRF-5 is required for the development of host-protective Th1 responses to L. donovani at later stages of infection." (PMID 21253574, 2011). "Why TLR7/IRF-5 activation is only required at later stages of infection and what role it plays in various T-cell subsets are two more questions that remain yet to be answered." (PMID 21253574, 2011). "Surprisingly, IRF-5-deficient p14 cells underwent clonal expansion similarly to WT p14 cells but failed to survive during the chronic stage of infection." (PMID 40494997, 2025). "Because these findings suggest that Irf5−/− p14 cells are more dysfunctional at d30 and 60 of infection than their IRF-5-sufficient counterpart, we next assessed whether these cells would show increased signs of exhaustion." (PMID 40494997, 2025). "Furthermore, nuclear localization of IRF5 was selectively enhanced in GFP+ cells with HIV WT infection, suggesting that cell-intrinsic HIV-1 icRNA sensing activates IRF5." (PMID 40493408, 2025). "Further studies are needed to confirm whether the downregulation of IRF5 expression in severe E11 infection is due to a specific viral component." (PMID 39045132, 2024). "In addition, IRF-3 and IRF-5 expression was significantly (p < 0.05) higher in cells treated pre-infection than in post-infection experiments." (PMID 37317211, 2023). "The expression of ATF2 and IRF5 transcription factors was downregulated by VSV-infection." (PMID 34578166, 2021).
infection (continued). "Infection with influenza virus markedly increases GlcNAcylation of IRF5 at serine 430 in human macrophages, which is essential for K63polyubiquitination of the same residue that activates IRF5, thus promoting proinflammatory cytokine expression and possibly increased viral replication." (PMID 33936053, 2021). "Given the established role for myeloid cells in pulmonary inflammation during IAV infection, we used polychromatic flow cytometry panels to assess whether Irf5 influenced myeloid cell accumulation during infection." (PMID 32075938, 2020). "Macrophages that lacked GEF-H1, IKKε, or IRF5 were significantly more susceptible to infection with L. monocytogenes." (PMID 30902986, 2019). "With ECO 17-1 infection there was a tendency for increased levels of nuclear IRF5, which might reflect a low TLR8-agonistic activity of this isolate." (PMID 31214180, 2019). "Either model supports the hypothesis that knockdown of Irf5 will improve healing of infections that induce an excessive inflammatory response." (PMID 29773788, 2018). "Nfkb1, lrf3, and Irf5 gene expression was barely influenced by TMEV infection." (PMID 26703877, 2015). "In the present study though, we show that the IRF-5-dependent inflammatory milieu induced by Leishmania during the first week of infection inhibits CD8+ T cell expansion and the development of SLECs by inducing HIF-1α in dendritic cells and consequently altering DC functions." (PMID 26046638, 2015). "In the monocytic cell line RAW264.7 we could also detect higher levels of Irf5 mRNA after infection, although the effect of the infection was lower than in MEFs (compare with S9 B Fig)." (PMID 25856589, 2015). "IRF5 upregulation appears to be required by different cells at different time of infection." (PMID 21811511, 2012). "This does not exclude, though, that other cell types such as DCs and macrophages may express IRF5 during earlier stages of infection." (PMID 21253574, 2011). "Moreover, Irf5-/- mice failed to develop typical Th1-type granulomas and to control infection in the liver, demonstrating a vital role for IRF-5 in the induction of the anti-parasitic response." (PMID 21253574, 2011). "Hence, we infected wild type (WT) and Irf5-/- mice and monitored the course of infection at several time points." (PMID 21253574, 2011). "Thus, we analyzed the cell-specific expression pattern of IRF-5 mRNA in the liver and the spleen at different time points during infection." (PMID 21253574, 2011). "Interestingly, the absence of IRF-5 mostly impacted CD8 T cell responses during the chronic phase of infection, when IRF-5 seems to act as a metabolic checkpoint and help CD8 T cells cope with the hostile environment created by the chronic inflammation and the continuous antigen stimulation." (PMID 40494997, 2025). "Therefore, we aimed to elucidate whether miR-146b controlled the polarization of M1 macrophages through IRF5 during CFT073 infection." (PMID 37909731, 2023). "Interestingly, we could not detect any upregulation of IRF-5 mRNA expression in splenic T-cells from infected Tlr7-/- mice at d28 p.i., suggesting that TLR7 is essential for the induction of IRF-5 in T-cells in the spleen at later stages of infection." (PMID 21253574, 2011). "To confirm that mitochondria were not functioning optimally in the absence of IRF-5 in vivo as well, we next assessed the ex vivo metabolic capacity of adoptively transferred Irf5−/− and WT p14 cells at d15 and 21 after LCMV Cl13 infection." (PMID 40494997, 2025). "Of the ISGs IFN-γ, IRF5, NMI, and IRF8, only the expression of IFN-γ changed during the course of infection." (PMID 39104769, 2024). "It has been shown that in a mouse model of infection with L. donovani, IFN-γ+ CD4+ T cells died by apoptosis via TLR7-mediated IRF-5 upregulation of DR5; the authors suggested that this was triggered by tissue disruption." (PMID 35106507, 2022).
infection (continued). "The genes IKBKB, IRAK3, IRF5, MAP2K4 (MEK4), MAPK14 (p38), MAPK8 (JNK1) and NFKB1 (p50) were upregulated not only in both cell types, but also after infection with whole bacteria of P. gingivalis W83 as well as with the membrane fraction." (PMID 28056810, 2017). "For example, different strains of S. aureus can activate different pattern recognition receptor (PRR) signaling cascades, specifically NOD2/IRF5 versus TLR9/IRF1, leading to different type I IFN responses that affect survival after infection." (PMID 27143388, 2016). "These experiments demonstrate that Irf5 is expressed in MEFs, BMDMs and RAW264.7 cells and that expression can be further induced in all our experimental systems by infection." (PMID 25856589, 2015). "Because only a very small percentage of splenic DCs bury parasites during acute infection, accumulation of HIF-1α mRNA in DCs is most likely due to the inflammatory milieu induced by IRF5." (PMID 26046638, 2015). "Upon infection with NDV, IRF5 binds to histone acetylase (HAT) proteins p300, CBP, and PCAF while SMRT is exported out of the nucleus." (PMID 23251221, 2012). "The contribution of IRF5 as well as IRF3 and IRF7 activation by IAV during infection and MDP treatment is the subject of ongoing investigation." (PMID 22590599, 2012). "IRF-5 is critical for immunity against some viruses, as IRF-5−/− mice have increased mortality and/or blunted systemic IFN production after infection with VSV, HSV, and NDV." (PMID 19798431, 2009). "Naive CD8 T cells purified from these mice and from the IRF-5 sufficient, Cre- p14 control mice (Irf5flox/flox x CMV-Cre−p14; herein called as WT p14) were then adoptively transferred into CD45.1 congenic mice a day prior to infection with LCMV Cl13." (PMID 40494997, 2025). "Nevertheless, the absence of IRF-5 significantly impacted the maintenance of IFN-γ-producing cells over the chronic stage of infection, when lower frequencies of IFN-γ+ cells and lower amounts of IFN-γ per cell were observed, compared with the control group." (PMID 40494997, 2025). "At this stage of infection, about 80% of the KLRG1+ cells were IRF-5+." (PMID 40494997, 2025). "Here, we show that IRF-5 prevents premature functional exhaustion and cell death by controlling the cell cycle and acting like a metabolic checkpoint in CD8 T cells during the chronic stage of infection." (PMID 40494997, 2025). "In our infection model, the absence of IRF-5 profoundly affected CD8 T cell responses to an extent that they are incapable of clearing LCMV Cl13 infection in the serum." (PMID 40494997, 2025). "Hence, we first monitored the expression of this transcription factor in murine CD8 T cells over the course of infection with LCMV Cl13, which establishes chronic infection in mice, and found that IRF-5 was indeed expressed by murine CD8 T cells." (PMID 40494997, 2025). "Of note, despite having an active infection and higher levels of systemic immune activation compared with HIVfree individuals, CD4+ T cells from EC donor expressed low levels of TLR7, insufficient to promote IRF-5 and cell death." (PMID 37227774, 2023). "Notably, the majority chemokine ligand, which induced cells of the immune system to enter the site of infection, CCL-2, CD80 and CD68 of TAMs, IRF5 and NOS2 of M1, CD163 and MS4A4A of M2 were strongly related to JAK1 expression in LUAD (all P value < 0.0001)." (PMID 34587898, 2021). "These signaling pathways showed that, after LPS infection, several DEGs were mainly related to immune function, such as up-regulated expression of CCL5, IL8, NFKBIA, TRAF3, and TNFAIP3, and down-regulated expression of MEF2C, MAP2K6, TLR1, TLR2, and IRF5." (PMID 34067819, 2021). "Although LysM-Cre mice are the model of choice to delete specific genes in myeloid cells, we were puzzled by the fact that deletion of Irf5 in myeloid cells did not have any effect at all on the immune response to L. donovani or on the course of infection." (PMID 32038622, 2019).
infection (continued). "We have previously reported that IRF-5-mediated inflammation was required to induce HIF-1α expression in dendritic cells and that this had an negative impact on their function and on CD8 T cell expansion during the first 10 days of infection." (PMID 32038622, 2019). "The linkage between TLR7 and LMP1 expression is intriguing: primary infection of B lymphocytes by EBV may induce the expression of TLR7, IRF5, and IRF7." (PMID 22952664, 2012). "This suggests that increased IRF-5 expression in T-cells is independent of TLR7 during the early stages of infection in the liver." (PMID 21253574, 2011). "Interestingly, mice with a T cell specific Irf5 ablation failed to clear infection in the serum, highlighting the severe CD8 T cell dysfunctionality." (PMID 40494997, 2025). "Specific single nucleotide polymorphisms (SNPs), such as PTPN22 rs2476601 and CTLA4 rs3087243, are associated with infection-triggered CFS/ME, while other SNPs, such as IRF5 rs3807306 and TNF rs1799724, have decreased allele frequencies in CFS/ME patients who do not have infection-triggered onset." (PMID 39483544, 2024). "Additionally, this study provided only a preliminary exploration of upstream factors affecting IFNα and IP10, necessitating further clinical data and animal experiments to reveal the regulatory roles of IRF5, IRF7, and IFNAR in severe E11 infection in neonates." (PMID 39045132, 2024). "Conversely, treatment with IRF5 inhibitor N5-1 significantly increased fungal burden in the kidneys and brains of Clec2dfl/flLyz2Cre/+mice, accompanied by decreased levels of IL-12 and IFN-γ in the kidneys of Clec2dfl/flLyz2Cre/+mice on Day 1 after infection with C. albicans." (PMID 37872182, 2023). "Our research indicated that infection, a family history of AD in FDR, a history of pregnancy, the CGGGG indel polymorphism in the IRF5 gene and negative stressful life events might be risk factors for pSS." (PMID 36534351, 2023). "Interestingly, iPSDMs had increased rates of infection with the knockout of IRF5 and IL10RA, indicating that stimulation of these factors might counteract infection." (PMID 32509598, 2020). "This disagreement with the literature could be explained by the fact that CD4 T cell responses are primed very late during infection and peak at d21–28 p.i., when IRF-5 is not strongly expressed by myeloid cells." (PMID 32038622, 2019). "Quantitative real time PCR (qRT-PCR) of RNA in SCC-25 cells after 24 h of infection with P. gingivalis total membrane showed statistically significant up-regulation of the following genes: IκBκB (4.7 ×), MAP2K4 (4.6 ×), MAPK14 (4.2 ×) and IRF5 (9.8 ×) (p < 0.01) (n = 9)." (PMID 28056810, 2017). "Work on Irf5 has been focused so far on lymphoid immune cells such as B-cells and DCs and therefore we asked whether Irf5 is expressed in MEFs and in monocytes (RAW264.7) and if the Irf5 expression in these cell systems is inducible by infection with MCMV." (PMID 25856589, 2015). "Therefore, since TLR3 and TLR4 molecules contribute to the generation of a normal IFN response through activation of IRF-3, IRF-5, and IRF-7 after infection with neurotrophic virus, we tested whether the ablation of TLR3 and TLR4 molecules affected type I innate responses in JEV infection." (PMID 25188232, 2014). "Interestingly, while Th1 responses in Irf5-/- mice were severely impaired 4 weeks after infection, expression of IRF-5 was not required during the first 2 weeks of infection, since the frequency of IFNγ-producing CD4+ T-cells in Irf5-/- mice was comparable to WT mice." (PMID 21253574, 2011). "We repeated this analysis using the virus only conditions and found that IRF5, but not IRF3 or IRF7, was significantly upregulated in HIV-1–infected MDMs isolated from older donors despite similar levels of infection in vitro." (PMID 40493408, 2025).